SH3PXD2B (SH3 and PX domains 2B)
Description:
Adapter protein involved in invadopodia and podosome formation and extracellular matrix degradation. Binds matrix metalloproteinases (ADAMs), NADPH oxidases (NOXs) and phosphoinositides. Acts as an organizer protein that allows NOX1- or NOX3-dependent reactive oxygen species (ROS) generation and ROS localization. Plays a role in mitotic clonal expansion during the immediate early stage of adipocyte differentiation (By similarity).
Synonyms: FAD49; KIAA1295; TKS4; FLJ20831; FTHS; HOFI; TSK4
Tractability: Antibody: the Human Protein Atlas places it where antibodies can reach. PROTAC: ubiquitination databases record sites on it; its protein half-life has been measured.
Gene: Protein-coding gene on chromosome 5 (172,325,000 to 172,454,531, reverse strand). Ensembl gene ENSG00000174705.
Subcellular location: Cytoplasm; Cell projection, podosome
Subcellular location (Human Protein Atlas): Plasma membrane; Cytosol; Nucleoplasm
Gene Ontology:
Molecular function: protein binding; phosphatidylinositol-3,5-bisphosphate binding; phosphatidylinositol-3-phosphate binding; phosphatidylinositol-5-phosphate binding; SH2 domain binding; superoxide-generating NADPH oxidase activator activity; phosphatidylinositol binding; phosphatidylinositol-4-phosphate binding
Biological process: bone development; extracellular matrix disassembly; eye development; heart development; protein localization to membrane; skeletal system development; superoxide metabolic process; adipose tissue development; podosome assembly; superoxide anion generation; cranial skeletal system development; osteoblast fate commitment; positive regulation of adipose tissue development; positive regulation of fat cell differentiation; positive regulation of gene expression; positive regulation of multicellular organism growth; positive regulation of stress fiber assembly; regulation of brood size; skeletal system morphogenesis
Cellular component: cytoplasm; podosome
Genetic constraint (gnomAD): Loss-of-function variants: 39 observed, 77.79 expected, observed/expected ratio (o/e) 0.5, 90% interval 0.39 to 0.65. The upper end of that interval is the gene's LOEUF score, 0.65, which puts it in group 2 of 6, group 1 being the genes least tolerant of losing a copy. Missense variants: 1,053 observed, 1,241.7 expected, observed/expected ratio (o/e) 0.85, 90% interval 0.81 to 0.89. Synonymous variants: 457 observed, 494.97 expected, observed/expected ratio (o/e) 0.92, 90% interval 0.85 to 1.
Gene-disease validity (ClinGen):
ClinGen rates the evidence that SH3PXD2B causes each of these diseases.
Frank-Ter Haar syndrome (autosomal recessive): Definitive.
Homologues: Orthologues: chimpanzee SH3PXD2B (99% identical), macaque SH3PXD2B (98% identical), dog SH3PXD2B (89% identical), rat Sh3pxd2b (88% identical), mouse Sh3pxd2b (88% identical), guinea pig SH3PXD2B (86% identical), rabbit SH3PXD2B (82% identical), pig SH3PXD2B (82% identical), tropical clawed frog sh3pxd2b (64% identical), zebrafish sh3pxd2b (56% identical). Paralogues in human: SH3PXD2A (42% identical), NCF1 (15% identical), NOXO1 (8% identical).